SERPINA1 (serpin family A member 1)
Diseases named in the same sentence as SERPINA1 in open-access papers (continued):
Sharing a sentence is not in itself a finding about the gene and the disease.
atherosclerosis (17 papers, 2012 to 2025). A disease characterized by the build-up of fatty material and calcium deposition in the arterial wall resulting in partial or complete occlusion of the arterial lumen. "We considered the SOST cis variant and B4GALNT3, SERPINA1, and RIN3 trans variants identified above as possible instruments for MR analyses of the effect of lower sclerostin levels on atherosclerosis risk." (PMID 37096546, 2023). "The latest study demonstrated six-fold enrichment of SERPINA1 in human atherosclerotic in contrast to healthy ones to verify the involvement of SERPINA1 in atherosclerosis." (PMID 36015199, 2022). "In 46 upregulated OCRGs in MDs, upregulation of two regulators VAMP8 and SERPINA1 was shared between obese and atherosclerosis; and two upregulated regulators DNM2 and MTFP1 were shared between T2D and atherosclerosis." (PMID 34368262, 2021). "SERPINA1 encodes alpha 1-antitrypsin (A1AT), a protease inhibitor that protects surrounding tissues at sites of inflammation, and various studies have suggested A1AT's role in atherosclerosis." (PMID 22916037, 2012). "Interestingly, Atherosclerosis Signaling was the second highest IPA pathway, and includes genes previously associated with vascular inflammation, such as IL-37, SERPINA1, S100A8, selectin E/SELE, lipoprotein lipase/LPL, and MMP1/3/9." (PMID 26459294, 2015). "Since genetic variation and gene expression of SERPINA1 and AQP9 were associated with lipoprotein levels, lipid transporters central to atherosclerosis, we investigated the relationship between these genes and atherosclerosis." (PMID 22916037, 2012). "The TVS results suggest that both AQP9 and SERPINA1 are candidate genes for atherosclerosis." (PMID 22916037, 2012). "Finally, we show that the genes are associated with atherosclerosis using mouse atherosclerotic lesion size (AQP9) as well as tissue from healthy human arteries and atherosclerotic plaques (AQP9 and SERPINA1)." (PMID 22916037, 2012). "In the genomic regions shared by GlycA and atherosclerosis, five nonsynonymous exonic SNPs were mapped to genes FGB, SLC22A1, LPL, SERPINA1, and ANGPTL4, with the following high PPs, H3: 94.5%, H4: 96.8%, H4: 73.7%, H4: 97.2%, and H4: 100%." (PMID 38892172, 2024). "We detected 7 novel loci and investigated the gene expression of our top loci, SERPINA1 and AQP9, in multiple human tissues as well as their potential role in atherosclerosis." (PMID 22916037, 2012). "Further functional work will need to be performed to elucidate the biological role of SERPINA1 and AQP9 in atherosclerosis." (PMID 22916037, 2012). "Interestingly, out of these, SERPINA1, SERPINE1, and SERPINF1 are known to positively correlate with atherosclerosis in humans." (PMID 35440683, 2022). "We also speculate that the roles of SERPINA1 and AQP9 in atherosclerosis are tissue-specific where AQP9 displays an effect in both liver and arterial tissue and SERPINA1 only in the latter." (PMID 22916037, 2012).
bladder cancer (17 papers, 2013 to 2025). "Reduced VEGF and increased SERPINA1 were associated with high-grade bladder cancer." (PMID 25387487, 2014). "Emerging evidence highlights its therapeutic potential in bladder cancer, osteosarcoma, and colon cancer, positioning SERPINA1 as a dual prognostic biomarker and actionable target." (PMID 40821817, 2025). "It has been reported that the expression of SERPINA1 was correlated with the prognosis of metastasis in a variety of cancers, including lung, colon, and bladder cancers." (PMID 34621293, 2021). "Relative to control cases, a reduction in SDC1 and overexpression of MMP9, MMP10, SERPINE1, IL8, APOE, SERPINA1, ANG were associated with high stage bladder cancer." (PMID 25387487, 2014). "SERPINA1 (alpha-1 antitrypsin) and H2B1K (histone H2B type 1-K) were discovered as promising bladder cancer biomarkers for prognosis using urine EVs and proteomic data from diseased patients versus healthy persons." (PMID 35159299, 2022). "Proteins alpha-1 antitrypsin (SERPINA1) and histone H2B type 1-K (H2B1K) have been identified from urinary exosomes as promising biomarkers for prognosis in bladder cancer." (PMID 33586060, 2021). "Some of the proteins such as SERPINA1, FGG, FGA, APOA1 and HP were also found with differential abundance in urine in proteomics studies of bladder cancer, and TYMP in tissue in renal cell carcinoma, but mostly with opposite abundance level compared to our study." (PMID 25653573, 2015).
autoimmune disease (16 papers, 2015 to 2026). A disorder resulting from loss of function or tissue destruction of an organ or multiple organs, arising from humoral or cellular immune responses of the individual to their own tissue constituents. "Recent studies have shown that SERPINA1 is closely associated with a variety of tumor diseases and autoimmune diseases such as ulcerative colitis and ANCA‐associated vasculitis." (PMID 39660984, 2024). "Finally, patients with pathogenic SERPINA1 defects exhibited a reduced probability of developing autoimmune disease (odds ratio: 0.17, p-value = 0.03) compared to those without pathogenic defects." (PMID 38791420, 2024). "Interestingly, in our study we observed that PAD patients with pathogenic SERPINA1 defects exhibit a significantly reduced probability of developing autoimmune disease compared to those without pathogenic defects." (PMID 38791420, 2024). "For instance, SERPINA1 can affect tumor necrosis factor α (TNF-α) signaling, which is critical in autoimmune diseases." (PMID 40294019, 2025).
Insulin resistance (16 papers, 2015 to 2025). Increased resistance towards insulin, that is, diminished effectiveness of insulin in reducing blood glucose levels. "It was shown to be decreased in serum of obese mice and human subjects and the imbalance between SERPINA1 and neutrophil elastase contributed to insulin resistance." (PMID 33526014, 2021). "Additionally, in the PCOS group, increased expression of SERPINA1 and SLC11A1 was found to be associated with insulin resistance and inflammation, respectively." (PMID 40790236, 2025).
ovarian carcinoma (15 papers, 1988 to 2025). A malignant neoplasm originating from the surface ovarian epithelium. "Previously, Wiseman and his colleagues reported that SERPINA1 can be diagnostic biomarker of thyroid cancer, and SERPINA1 has been recently reported to be involved in several other cancers including gastric, liver, pancreas, breast, lung, and ovarian cancers." (PMID 36430241, 2022). "Peptides and/or phosphopeptides of common plasma proteins such as HPR, HP, HPX, and SERPINA1 showed increased observation frequency and/or precursor intensity in ovarian cancer." (PMID 30598658, 2018). "The results showed that Snail and serpinA1 induced migration in both breast and ovarian cancer cells." (PMID 26015410, 2015). "In addition, SERPINA1 has also been reported to be involved in the regulation of ovarian cancer cell migration and invasion." (PMID 34692659, 2021). "In agreement with the literature, peptides from many common proteins including acute phase response proteins such as Haptoglobin (HP), Haptoglobin Related Protein (HPR), Alpha Anti Trypsin (SERPINA1) and others were more frequently observed in ovarian cancer samples." (PMID 30598658, 2018). "Moreover, we also observed that serpinA1 promoted migration in breast and ovarian cancer cell lines." (PMID 26015410, 2015). "In addition, the results of ChIP assays showed that Snail may also modulate serpinA1 expression by binding to the serpinA1 promoter in breast and ovarian cancer cells." (PMID 26015410, 2015). "Further analysis using ChIP assays revealed that Snail regulated the expression of serpinA1 through directly binding to the serpinA1 promoter not only in CRC cells but also in breast and ovarian cancer cells." (PMID 26015410, 2015). "Since Snail and serpinA1 are expressed not only in CRC but also in other types of cancer, we also examined the role of Snail and serpinA1 in breast and ovarian cancer cells (MCF7, MDA-MB-231, A2780, and SKVO3 cells) by modulating their expression." (PMID 26015410, 2015). "Therefore, IGFBP1, FBN1, SERPINA1 not only have complex interactions with WT1, but also may jointly regulate the migration and invasion of ovarian cancer cells." (PMID 34692659, 2021).
pulmonary fibrosis (15 papers, 2011 to 2024). Chronic progressive interstitial lung disorder characterized by the replacement of the lung tissue by connective tissue, leading to progressive dyspnea, respiratory failure, or right heart failure. "SERPINA1 gene expression has been reported as associated to pulmonary fibrosis and regulation of immune response." (PMID 32899126, 2020).
Sepsis (14 papers, 2014 to 2024). Sepsis is defined as life-threatening organ dysfunction caused by a dysregulated host response to infection. "Notably, SLX4 hypomethylation showed the highest predictive value for poor prognosis (AUC 0.821), while SERPINA1 hypomethylation exhibited strong diagnostic potential for sepsis (AUC 0.858)." (PMID 39926115, 2024). "SAA1;SAA2, CRP, ITIH3, SERPINA1 are acute phase proteins that are also dysregulated in other inflammatory states including sepsis." (PMID 36812516, 2022). "However, in our study PCT was the best biomarker for sepsis diagnosis (AUC 0.925), followed by SERPINA1 (AUC 0.858)." (PMID 39926115, 2024). "Some studies have analyzed SERPINA1 expression as a potential biomarker in sepsis." (PMID 39926115, 2024). "SERPINA1, AZU1, MPO and SLX4 genes stand out for their correlation with inflammation and severity and have potential as biomarkers for diagnosing sepsis and predicting poor prognosis." (PMID 39926115, 2024). "Based on their high differential methylation levels and their role in the immune functions identified, four genes (SERPINA1, AZU1, MPO and SLX4) were selected for further validation, supported by available evidence of their biological roles in sepsis." (PMID 39926115, 2024). "Overall, these findings underscore the potential of DNA methylation as biomarkers in sepsis, particularly for AZU1, MPO, SERPINA1, and SLX4, which show strong correlations with clinical indicators of severity and inflammation." (PMID 39926115, 2024). "Extensive experiments are needed to verify the clinical application of SERPINA1 and GPX‐3 in sepsis and uncover the mechanisms of them as a biomarker for sepsis." (PMID 34825737, 2022). "We observed an increased SERPINA1 (P < 0.05) and decreased SERPINF2 (P < 0.05) in the PF patient compared with the healthy individuals and the burn sepsis patients, which was similar to the HPLC-chip/MS results." (PMID 24659849, 2014). "In 26 upregulated OCRGs in AIs, the upregulation of two regulators, SERPINA1 and AZU1, was shared among acute respiratory distress syndrome (ARDS), sepsis, and trauma; upregulation of CD24 and FKBP8 was shared among ARDS and trauma; and upregulation of GRN was shared between sepsis and trauma." (PMID 34368262, 2021).
glioma (13 papers, 2015 to 2025). A benign or malignant brain and spinal cord tumor that arises from glial cells (astrocytes, oligodendrocytes, ependymal cells). "Comprehensive bioinformatics investigations have identified the SERPINA1 glycosylation gene as one of seven glycosylation genes associated with glioma prognosis, indicating its involvement in cytokine signaling, inflammatory responses, immunological control, glycan synthesis, and metabolic pathways." (PMID 39851516, 2025). "However, higher SERPINA1 expression was associated with poorer OS in GBMLGG (glioma), GBM, HNSC, KICH, LGG (brain lower-grade glioma), LIHC, and LUSC." (PMID 37511325, 2023). "As glioma advances, the SERPINA1 glycosylation gene contributes to the heightened infiltration of diverse immune cells, including macrophages." (PMID 39851516, 2025). "In the present work, we confirmed that NQO1 functions as an RNA-binding protein (RBP) that binds with SERPINA1 mRNA and enhances its translation, facilitating the proliferation of glioma cells by reducing the apoptosis." (PMID 36349191, 2022). "In conclusion, our findings showed that oncogene NQO1 and antioncogene miR-1321 bind to oncogene SERPINA1 to affect proliferation and apoptosis of glioma cells, which can bring new solution of antitumor treatments for glioma in the future." (PMID 36349191, 2022). "NQO1 binds with SERPINA1 mRNA and significantly increases its translation, thus boosting glioma tumorigenesis." (PMID 36349191, 2022). "Serpin family A member 1 (SERPINA1) is expressed abundantly in gliomas and can predict unfavorable prognosis of patients with glioma." (PMID 36349191, 2022). "The survival analysis suggested that glioma patients with high level of SERPINA1 expression had poor survival." (PMID 36349191, 2022). "The expression of SERPINA1 at the messenger RNA (mRNA) and protein levels was also measured in NHA and four glioma cell lines, which showed that the expression of SERPINA1 was increased remarkably in glioma cells." (PMID 36349191, 2022). "The results of function assays showed that SERPINA1 increased glioma cell proliferation by suppressing apoptosis." (PMID 36349191, 2022). "Influences of NQO1, SERPINA1, and miR-1321 on the proliferation and apoptosis of glioma cells were assessed." (PMID 36349191, 2022). "In this study, we used short hairpin RNAs (shRNAs) to determine the effects of SERPINA1 on the proliferation and apoptosis of glioma cells." (PMID 36349191, 2022). "Then, colony formation assay was taken to analyze the impact of SERPINA1 silence on the proliferation of glioma cells." (PMID 36349191, 2022). "SERPINA1 was found to be related to macrophages in glioma immunological microenvironments." (PMID 39851516, 2025). "In this study, we explored the functions of SERPINA1 in glioma tumorigenesis in vitro and then investigated whether NQO1 affects the protein expression of SERPINA1 and its mRNA level." (PMID 36349191, 2022). "In addition, SERPINA1 expression was also found to be higher in malignant high-grade glioma, which correlated with poor prognosis for patients." (PMID 35109832, 2022). "An immunostaining result demonstrates the expression of SERPINA1 in gliomas." (PMID 36349191, 2022). "SERPINA1 was shown to be expressed in glioma tissue samples." (PMID 36015199, 2022). "Studies have shown that nicotinamide adenine dinucleotide phosphate quinone dehydrogenase 1 (NQO1) can promote the proliferation of glioblastoma multiforme cells and enhance the expression of SERPINA1, but its effects on glioma cells remain unknown." (PMID 36349191, 2022). "We found that high expression of SERPINA1 marks poor overall survival in glioma." (PMID 36349191, 2022). "Alpha-1 antitrypsin, the protein encoded by SERPINA1, is synthesized mainly by pulmonary alveolar cells, macrophages, and hepatocytes and modulates protease and corresponding inhibitors to defend glioma cells from host offense." (PMID 36349191, 2022).
glioma (continued). "The results showed that in glioma cells, apoptosis rate was increased when SERPINA1 was silenced." (PMID 36349191, 2022). "Using the GEPIA dataset, we obtained SERPINA1 expression in glioma tumors and normal tissues." (PMID 36349191, 2022). "Furthermore, by using four glioma cell lines (U251, T98G, LN-229, and A172), it has been shown that the interplay between NQO1 and the anti-oncogenic miR-1321 with the oncogene serpin family A member 1 has been shown to impact the proliferation and apoptosis of glioma cells." (PMID 38167027, 2024). "We made a hypothesis that NQO1 binds to SERPINA1 to play an oncogenic role in glioma cells." (PMID 36349191, 2022). "Moreover, SERPINA1 rescued the effects of sh-NQO1 in glioma cell malignant phenotypes." (PMID 36349191, 2022). "Considering the pro-proliferative and anti-apoptotic effects of SERPINA1 in glioma, we had the hypothesis that by upregulating the expression of SERPINA1, NQO1 would enhance the proliferation of glioma cells and suppress apoptosis, and such hypothesis was confirmed by the rescue assays." (PMID 36349191, 2022). "Finally, SERPINA1 is a key anti-inflammatory player reported to promote invasiveness and progression in a wide range of cancers and to be a prognostic marker of poor overall survival in high-grade gliomas." (PMID 35052804, 2022). "By identifying differentially expressed genes (DEGs) between subtypes, we constructed a four-gene prognostic signature (MAOB, IGFBP2, SERPINA1, and LGR6) and validated its robustness using the Chinese Glioma Genome Atlas (CGGA) expression dataset." (PMID 40821817, 2025). "We established and validated a robust four-gene signature (MAOB, IGFBP2, SERPINA1 and LGR6) that serve as an independent prognostic biomarker for grade II/III gliomas." (PMID 40821817, 2025). "Finally, functional experiments were performed to evaluate the roles of risk genes in the cell viability of glioma cells, which demonstrated that silencing BGN, SDC1, SERPINA1, TUBA1C, C1GALT1C1L and SPTBN5 could inhibit the growth and viability of glioma cells." (PMID 38396140, 2024). "However, the property of the binding of NQO1 to SERPINA1 in glioma cells remains unknown." (PMID 36349191, 2022). "In conclusion, our work demonstrates that in glioma cells, NQO1 enhances the translation of SERPINA1 mRNA by binding with 3′UTR and thus promotes the function of SERPINA1 by suppressing apoptosis and enhancing the proliferation." (PMID 36349191, 2022). "SERPINA1 and NQO1 promoted glioma cell proliferation and suppressed cell apoptosis." (PMID 36349191, 2022). "sh-NQO1 did not affect SERPINA1 mRNA but decreased its protein expression in primary glioma cells." (PMID 36349191, 2022). "Moreover, functional experiments were performed to evaluate the roles of risk genes in the cell viability and cell number of glioma U87 and U251 cells, which demonstrated that silencing BGN, SDC1, SERPINA1, TUBA1C, C1GALT1C1L and SPTBN5 could inhibit the growth and viability of glioma cells." (PMID 38396140, 2024). "To validate the protein-level expression patterns of the prognostic genes in clinical specimens, we performed immunohistochemical (IHC) staining of MAOB, IGFBP2, SERPINA1, and LGR6 on paraffin-embedded sections of glioma tissues and adjacent non-tumorous brain tissues." (PMID 40821817, 2025).
Hepatic steatosis (13 papers, 2015 to 2025). Steatosis is a term used to denote lipid accumulation within hepatocytes. "Single nucleotide polymorphisms (SNPs), including PNPLA3 rs738409 and SERPINA1 rs17580, have been identified as risk modifiers in the progression fatty liver disease (alcoholic (ALD) or non-alcoholic (NAFLD))." (PMID 33804385, 2021).
colon carcinoma (12 papers, 2014 to 2025). "Based on the earlier conducted functional enrichment analysis, we noticed that TIMP1, PF4 and SERPINA1 share a role in platelet degranulation, suggesting a key role for this biological process in colon cancer survival." (PMID 35008327, 2021). "This is consistent with our findings that SERPINA1 could serve as a biomarker to predict the overall survival in colon cancer." (PMID 34315829, 2021). "We obtained the risk score of each case with colon cancer; risk score = (0.46121 × expression of ULK3) + (0.650715 × expression of ATG101) + (1.521474 × expression of MAP1LC3C) + (0.641122 × expression of TSC1) + (0.243022 × expression of DAPK1) + (-0.17015 × expression of SERPINA1)." (PMID 34315829, 2021). "Specifically, CDC25C, ANKRD22, SEZ6L2, SERPINA1, and NOS2 were overexpressed in colon cancer tissues compared with normal tissues." (PMID 41425595, 2025). "We identified 6 prognostic-related ARGs (ULK3, ATG101, MAP1LC3C, TSC1, DAPK1 and SERPINA1) to formulate a novel autophagy-related signature, which could stably predict the survival of patients and indicate the extent of immunosuppressive microenvironment in colon cancer." (PMID 34315829, 2021).